RNU6-1000P (RNA, U6 small nuclear 1000, pseudogene)
Gene: Small nuclear RNA gene on chromosome 4 (76,356,610 to 76,356,715, reverse strand). Ensembl gene ENSG00000212368.
Homologues: Orthologues: chimpanzee U6 (100% identical), macaque U6 (98% identical). Paralogues in human: RNU6-12P (84% identical), RNU6-13P (84% identical), RNU6-32P (84% identical), RNU6-7 (84% identical), RNU6-8 (84% identical), RNU6-1 (83% identical), RNU6-17P (83% identical), RNU6-18P (83% identical), RNU6-2 (83% identical), RNU6-31P (83% identical), RNU6-3P (83% identical), RNU6-45P (83% identical), and 1288 more.